HPSE (heparanase)
Diseases named in the same sentence as HPSE in open-access papers (continued):
Sharing a sentence is not in itself a finding about the gene and the disease.
pancreatic cancer (26 papers, 2002 to 2025). "Ionizing radiation treatment of PANC1 pancreatic carcinoma cells determined an increase in Egr1 (Early Growth Response Protein 1), which in turn caused repression of heparanase transcription." (PMID 34249755, 2021). "For instance, in pancreatic cancer, increased levels of heparanase – the enzyme that cleaves HS GAGs, have been implicated in angiogenesis and metastasis, and correlated with poor prognosis." (PMID 33330449, 2020). "Pancreatic tumor cells overexpressing heparanase were implanted into severe combined immune deficiency (SCID) mice, which lack B and T cells." (PMID 31110966, 2019). "In a mouse model of pancreatic cancer, HPSE overexpression was associated with increased macrophage expression of M2 cytokines IL-6, IL-10, CCL-2, VEGF, and macrophage scavenger receptor-2 (MSR-2), increased tumor size, and increased levels of tumor-infiltrating macrophages." (PMID 34461608, 2021). "The heparanase inhibitor roneparstat was used to demonstrate the role of heparanase in relapse and persistence of pancreatic cancer." (PMID 34249755, 2021). "Animals bearing an orthotopic model of pancreatic cancer were irradiated and treated with the heparanase inhibitor: tumor growth was significantly reduced with respect to untreated animals." (PMID 34249755, 2021). "In a mouse model of pancreatic carcinoma with Panc02, highly expressing heparanase, the heparanase inhibitor showed substantial anti-tumor activity." (PMID 34249755, 2021). "Ionizing radiation was shown to augment the invasive phenotype of pancreatic carcinoma cells in vitro and in vivo by upregulating heparanase." (PMID 34249755, 2021). "In a clinical study, patient samples of chronic pancreatitis showed a high expression of HPSE, which increased further in cases of pancreatic cancer, resulting in poor post-operative survival." (PMID 33256730, 2020). "Wnt: HPSE has been shown to mediate Wnt signalling in cancer settings via studies on medulloblastoma and pancreatic cancer." (PMID 33256730, 2020). "In a 2018 study, HPSE mRNA in the peripheral blood mononuclear cell fraction and HPSE activity in plasma and urine were detected in 31 patients with pancreatic cancer." (PMID 31327867, 2019). "Implanted tumors with heparanase-overexpressing pancreatic cancer cells were observed to have more infiltrating macrophages and larger tumors compared to tumors with normal heparanase expression." (PMID 31110966, 2019). "Pancreatic cancer patients whose tumors exhibit high levels of heparanase mRNA had a significantly shorter postoperative survival time than patients whose tumors contained relatively low levels." (PMID 31921662, 2019). "Heparanase is a highly significant independent variable for lymph node metastasis in pancreatic cancer patients, further supporting crucial involvement of the enzyme in PDAC progression." (PMID 31921662, 2019). "The overexpression of heparanase in these pancreatic tumors also led to increased macrophage expression of IL-6, IL-10, C-C motif chemokine ligand-2 (CCL-2), vascular endothelial growth factor (VEGF) and macrophage scavenger receptor-2 (MSR-2)." (PMID 31110966, 2019). "Given deterioration in glycemic control in a majority of PDAC patients, these findings provide molecular explanation for induction of heparanase in pancreatic carcinoma." (PMID 31921662, 2019). "Heparanase, which is an endoglycosidase that cleaves heparan sulfate (HS) glycosaminoglycans, can also guide cancer-promoting action of TAM by augmenting STAT3 signaling in vitro and in a mouse model of heparanase-overexpressing pancreatic carcinoma." (PMID 27191744, 2016). "We examined eight human pancreatic cancer cell lines from different tissues of origin for the expression of heparanase mRNA and protein." (PMID 11953884, 2002).
pancreatic cancer (continued). "In the intent to determine the prognostic value of heparanase in pancreatic cancer, we have analysed heparanase expression, stage of disease and survival of those 26 patients, that had been curatively resected (R0 resection)." (PMID 11953884, 2002). "However, LMWHs are known to inhibit heparanase, an endoglycosidase rarely expressed in normal tissue but overexpressed in pancreatic tumors." (PMID 34208987, 2021). "The opposite was observed in a model of pancreatic cancer overexpressing heparanase." (PMID 31110966, 2019). "Given the high affinity binding of Wnt ligands to HS and the link between altered HSPGs, heparanase, and tumor cell metastasis, investigating HS mimetics/heparanase inhibitors effect on Wnt signaling was considered a novel approach to discover new therapeutic options for pancreatic carcinomas." (PMID 25669977, 2015). "Therefore, we have analysed the expression of heparanase in human pancreatic cancer tissue and cell lines." (PMID 11953884, 2002). "Our results suggest, that heparanase promotes cancer cell invasion in pancreatic carcinoma and could be used as a prognostic indicator for postoperative survival of patients." (PMID 11953884, 2002). "Heparanase inhibitors may be effective against tumors in which leukocyte-heparanase aids tumor progression, such as colorectal and pancreatic carcinoma, but perhaps less effective against other solid tumors which have little heparanase expression in the tumor microenvironment." (PMID 31110966, 2019). "Many factors are involved in transforming pancreatic cancer into a highly aggressive and metastatic disease, such as alterations in cell-cell interaction, deregulated expression of extracellular proteases, and metastasis-associated genes such as KAI-1, heparanase and a number of other molecules." (PMID 15710044, 2005). "In terms of its immunomodulatory activity on TAMs, there is preclinical evidence that heparanase may be responsible for this activity and is known to direct the tumor-promoting behaviour of TAMs in pancreatic cancer, and promote disease progression in pancreatitis and pancreatic cancer." (PMID 29898788, 2018). "A HS mimetic M402 currently in Phase I/II trials in pancreatic cancer was designed to inhibit tumor-host interactions including VEGF, FGF2, SDF-1 and heparanase." (PMID 25669977, 2015). "Although much of this activity has been attributed to inhibition of heparanase and heparan sulfate-binding growth factors, it was hypothesized that PG545 may additionally disrupt Wnt signaling, an important pathway underlying the malignancy of pancreatic cancer." (PMID 25669977, 2015). "Besides induction of heparanase in pancreatic tumor cells due to PDAC-triggered impairment of glucose homeostasis, this connection involves heparanase-empowered activation of the INSR-AKT signaling cascade." (PMID 38078007, 2023). "Here we show that in PDAC elevated levels of heparanase, coupled with diabetic conditions typical for PDAC patients, promote growth and chemotherapy resistance of pancreatic carcinoma by favoring insulin receptor signaling and GLUT4-mediated glucose uptake into tumor cells." (PMID 38078007, 2023). "Pancreatic cancers were shown to have heparanase mRNA levels more than 30-fold higher than the levels in normal pancreatic tissues." (PMID 32121387, 2020). "In addition to these studies on Roneparstat, another heparanase inhibitor, PG545, was recently shown to enhance the anticancer activity of chemotherapies in animal models of ovarian and pancreatic cancer." (PMID 26624982, 2016). "For example, in pancreatic cancer, HPSE was found to be overexpressed throughout the process of ionising radiotherapy, resulting from the downregulation of the transcription factor EGR1, which leads to the upregulation of HPSE and promotes tumour cells invasion." (PMID 33494442, 2021).
pancreatic cancer (continued). "Thus, to investigate heparanase regulation in PDAC under dysregulated glucose metabolism, we utilized a murine experimental system, based on Panc02 mouse pancreatic carcinoma cells growing in C57BL/6J mice with the diet-induced metabolic syndrome, as described in Methods." (PMID 31921662, 2019). "Given abundant evidence implicating heparanase in PDAC pathogenesis/aggressiveness/therapy resistance, our finding may provide a partial explanation for the mechanism through which diabetic state contributes to pancreatic carcinoma progression." (PMID 31921662, 2019). "Collectively, our findings underscore previously unknown mechanism through which heparanase acts at the interface of systemic and intracellular metabolic alterations in PDAC and attest the enzyme as an important and potentially modifiable contributor to the chemo-resistance of pancreatic tumors." (PMID 38078007, 2023).
bladder cancer (25 papers, 2009 to 2024). "HPSE mRNA levels in bladder cancer tissues related to tumor stage, histological grade, size, number, recurrence and lymph node metastasis." (PMID 34461608, 2021). "The HPSE expression also showed a medium positive correlation with M2 macrophages, monocytes, NK cells, exhausted T cells, and Th1 and Th17 cells in bladder cancer." (PMID 34461608, 2021). "By circHIPK3 enforced expression, the authors showed that this circRNA suppresses invasion, metastasis, and angiogenesis of bladder cancer cells, by repressing heparanase (HPSE) expression via sponging miR-558." (PMID 34356060, 2021). "CircHIPK3 overexpression resulted in an evident reduction of aggressiveness and metastasis in bladder cancer via regulating miR-558/heparanase axis." (PMID 33397365, 2021). "We have next examined the behavior of RT4 bladder carcinoma cells following the addition of our purified heparanase and Hpa2 proteins to the cell culture medium." (PMID 33585253, 2020). "In combination, these observations indicate that heparanase is a potential candidate for targeted therapy in bladder cancer." (PMID 32471161, 2020). "In our study, increased expression of heparanase in bladder cancer tissue samples correlated with higher recurrence rates within the bladder and progression to muscle-invasive cancer." (PMID 32471161, 2020). "The migration/invasion of bladder cancer cells and the production of heparanase were inhibited by circHIPK3 through sponging miR-558." (PMID 32847606, 2020). "In N-butyl-N-(4-hydroxybutyl) nitrosamine (BBN)-induced bladder cancer mice, treatment with heparanase inhibitor suppressed the progression of cancer by 40%, compared to controls." (PMID 32471161, 2020). "The immunohistochemical staining of surgically resected specimens from 47 bladder cancer patients showed that positive heparanase expression was observed predominantly in cases exhibiting intravesical relapse (p < 0.05)." (PMID 32471161, 2020). "The patterns of heparanase expression in resected bladder cancer tissue samples were analyzed using immunohistochemical (IHC) staining." (PMID 32471161, 2020). "Enforced overexpression of circHIPK3 significantly inhibited the migration, invasion, and angiogenesis of bladder cancer cells via sponging miR-558 to suppress the expression of heparanase (HPSE) and its downstream targets MMP-9 and VEGF." (PMID 31973726, 2020). "In the spontaneous bladder cancer mouse model, heparanase inhibition significantly suppressed bladder cancer invasion." (PMID 32471161, 2020). "Urinary heparanase levels, determined by this sensitive and simple method, were markedly elevated in patients with leukemia and bladder carcinoma." (PMID 26569485, 2015). "The result is quite consistent with previous studies regarding the regulation of heparanase by promoter methylation in prostate and bladder cancers." (PMID 24632672, 2014). "In bladder cancer cells upregulation of heparanase expression is shown to occur in a stepwise manner where hypomethylation of the heparanase gene promoter facilitates Egr-1 binding, which is shown to directly regulate the heparanase expression." (PMID 19878561, 2009). "Furthermore, in the spontaneous bladder cancer mouse model, heparanase silencing significantly suppressed bladder cancer invasion." (PMID 36340029, 2022). "Inhibition of HPSE expression suppressed invasion, migration and adhesion of bladder cancer cells." (PMID 34461608, 2021). "However, heparanase activity alone does explain changes in migration, invasion, and autophagy in bladder cancer cells." (PMID 32471161, 2020). "Notably, adhesion of the bladder carcinoma cells to Hpa2-, and to a lesser extent to heparanase-coated dishes was attenuated markedly by heparin (second and fourth panels)." (PMID 33585253, 2020).
bladder cancer (continued). "In addition, overexpression of circHIPK3 effectively inhibited migration, invasion, and angiogenesis of bladder cancer cells in vitro and suppressed bladder cancer growth and metastasis in vivo, mainly through targeting the miR-558/heparanase axis." (PMID 29349062, 2017). "Mechanistically, circHIPK3 sponged miR-558 to hinder heparanase (HPSE) expression, reducing the development of bladder cancer cells." (PMID 36292157, 2022). "Analysis of HPSE expression and prognosis in different cancers using the GEIPA database showed that high HPSE expression was related to poor DFS and OS rates in bladder cancer." (PMID 34461608, 2021). "A role for Egr-1 in human bladder cancer progression would be expected from the fact that Egr-1 regulates heparanase and HYAL-1 hyaluronidase expression in human bladder cancer cells." (PMID 19878561, 2009). "CircHIPK3 (hsa_circ_0000284) could function as the sponge of miR-558 to negatively regulate the expression of heparanase (HPSE), further inhibiting angiogenesis of bladder cancer cells." (PMID 38177102, 2024). "CircIMPACT analysis identified HPSE dysregulation according to circHIPK3 expression reduction in bladder cancer, in line with the non-canonical regulatory axis previously proven and linked to the disease." (PMID 34356060, 2021). "Similarly, bladder carcinoma cells RT4 and MBT2-t50 adhered efficiently to dishes coated with Hpa2, heparanase, and fibronectin (upper and third panels)." (PMID 33585253, 2020). "Other studies showed that the over-expression of circHIPK3 induced efficiently interaction with miR-558 and then down-regulated the expression of HPSE and its downstream targeted MMP-9 and VEGF to attenuate the promoting effect of miR-558 on bladder cancer cell migration, invasion, and angiogenesis." (PMID 30134837, 2018). "This is the exact opposite of heparanase expression pattern, which is not detected in the normal bladder but is highly expressed in bladder carcinoma, correlating with disease progression." (PMID 26968815, 2016). "Collectively, our results suggest that Hpa2 functions as a tumor suppressor in bladder cancer, maintaining cellular differentiation and decreasing cell motility in a manner that appears to be independent of regulating heparanase activity." (PMID 26968815, 2016).
atherosclerosis (23 papers, 2011 to 2026). A disease characterized by the build-up of fatty material and calcium deposition in the arterial wall resulting in partial or complete occlusion of the arterial lumen. "Recent evidence suggests a multifactorial role for heparanase in atherosclerosis by promoting underlying inflammatory processes giving rise to plaque formation, as well as regulating lesion stability." (PMID 36291066, 2022). "HPSE has also been implicated in the severity of atherosclerosis, as expression is increased in coronary vulnerable plaques as opposed to stable plaques and controls." (PMID 25295599, 2014). "HPSE has been implicated in inflammatory disorders including arthritis, multiple sclerosis, inflammatory bowel disease and atherosclerosis." (PMID 25295599, 2014). "Such a model, involving HPSE gene-deficient mice on the atherosclerosis prone ApoE−/− background would be an essential tool with which to gain a deeper understanding of the precise pathogenic role HPSE plays in driving atherosclerosis." (PMID 36291066, 2022). "Heparanase has been linked to multiple pro-atherogenic processes including restenosis following vascular injury and stenting, thrombosis, and has been associated with vulnerable plaque morphology in a diabetic, hyperlipidemic porcine model of atherosclerosis." (PMID 30417001, 2018). "Not surprisingly, the major proinflammatory cytokines involved in RA pathogenesis, TNF-α and IL-1, have been shown to upregulate heparanase expression in endothelial cells, which may be a potential cause of an increased risk of atherosclerosis associated with this arthropathy." (PMID 35887981, 2022). "Heparanase is also involved in the pathogenesis of inflammation, kidney dysfunction, fibrosis, atherosclerosis, and viral infection, supporting the notion that heparanase is a valid drug target." (PMID 40940793, 2025). "In summary, heparanase inhibitors apparently have the potential to treat cases of liver steatosis and fibrosis as well as atherosclerosis and are worth being further investigated as a new therapeutic modality in clinical trials." (PMID 35329997, 2022). "Of these inhibitors, PG545, a tetrasaccharide heparan sulfate mimetic molecule that inhibits heparanase activity, significantly decreased serum OS in the atherosclerosis animal model." (PMID 35329997, 2022). "This review provides an up-to-date overview of the role of heparanase in physiological and pathological processes with a focus on the emerging role of the enzyme in atherosclerosis." (PMID 36291066, 2022). "For further interpretations, see please “Heparanase inhibition attenuates atherosclerosis progression and liver steatosis in E0 mice”." (PMID 30238043, 2018). "Emerging evidence highlights a role of the enzyme heparanase in various disease states, including atherosclerosis formation and progression." (PMID 29226146, 2017). "Together, heparanase emerges as a regulator of vulnerable lesion development and potential target for therapeutic intervention in atherosclerosis and related vessel wall complications, possibly involving resistin." (PMID 24465803, 2014). "This lies in accordance with increasing awareness of the significance of heparanase in atherosclerosis and heart diseases." (PMID 24465803, 2014). "Over-expression of the heparanase gene indicates the importance of HSPGs for the uptake of TRPs and its protective effect on fatty streak formation and potentially atherosclerosis initiation." (PMID 21483695, 2011). "Notwithstanding the limitations of the dietary model of murine atherosclerosis, we were able to show the effects of heparanase over-expression on lipoprotein metabolism and fatty streak formation." (PMID 21483695, 2011). "This study investigated the impact of heparanase gene-deficiency on atherosclerosis development in non-diabetic and streptozotocin (STZ)-treated, diabetic apolipoprotein E gene knockout (ApoE-/-) mice fed a normal chow diet for eight weeks." (PMID 42290526, 2026).